IL6 (interleukin 6)
Diseases named in the same sentence as IL6 in open-access papers (continued):
Sharing a sentence is not in itself a finding about the gene and the disease.
kidney damage (continued). "Elevated CCR2 could increase the expression of multiple cytokines and chemokines, such as MCP-1, IL-6 and TNF alpha, and induces mesangial cell proliferation and matrix deposition, and further aggravate kidney damage." (PMID 35725391, 2022). "In addition, damaged mesangial cells release pro-inflammatory factors, such as IL-6, MCP-1, TNF-α and so on, which promotes the inflammatory response, and further aggravates kidney damage." (PMID 35725391, 2022). "Immune complexes and necrotic cells can activate innate immune receptors and promote the differentiation of M1 macrophages, which promotes a series of inflammatory responses and leads to kidney damage by secreting proinflammatory cytokines such as TNF-α, IL-1, IL-6, IL-12, and chemokines." (PMID 36059518, 2022). "Previous studies have indicated that the levels of TNF-α and IL-6 are significantly elevated in patients with DN, as compared with hyperglycemic patients without nephropathy." (PMID 32076626, 2020). "Studies have suggested that a persistent inflammatory response mediated by pro-inflammatory cytokines such as interleukin 1 beta (IL-1β), interleukin 6 (IL-6) and tumor necrosis factor alpha (TNF-α) contributes to the perpetuation of kidney damage (Furuichi, Kaneko & Wada, 2009)." (PMID 31275747, 2019). "Consistent with these experimental observations, here we found that OPG delivery significantly increased the gene expression of IL-6 and TGF-β, as well as the amount of protein nitrosylation in the kidney, which are all involved in kidney damage development and progression." (PMID 28683789, 2017). "Our data suggest C/EBP-α exerts anti-inflammatory effects through the inhibition of MCP-1 and IL-6 expression in podocytes, which may be the basis of the observed renorotective effects of C/EBP-α against the progression of ADR-induced nephropathy in mice." (PMID 27644413, 2016). "These include regulating glycolipid metabolism, suppressing inflammation (↓TNF-α/IL-6), improving insulin sensitivity (↓HOMA-IR), and enhancing vascular function (↑NO/FMD), while concurrently alleviating complications such as retinopathy, nephropathy, and sexual dysfunction." (PMID 41001671, 2025). "Similarly, apigenin has been demonstrated to reduce IL-6, TNF-α, and IL-1β levels, and increase IL-10 levels in the kidneys or serum in doxorubicin-induced male nephropathy BALB/c mice or in furan-induced nephropathy mice." (PMID 36422572, 2022). "Previous research found that the level of IL-6 in serum was significantly higher in diabetic patients with nephropathy than in diabetic patients without nephropathy, implying that IL-6 may play a role in the pathogenesis of DN." (PMID 35502173, 2022). "In the present study, an elevation of the serum values of IL-1β, IL-6 and TNF-α was observed as the degree of renal damage induced by FA progressed; this is consistent with the histological findings of an increase in inflammatory infiltrates as the degree of kidney damage increased." (PMID 31275747, 2019). "Thus, the suppression on IL-6 and TNF-α could retard or alleviate inflammation and improve nephropathy." (PMID 24886259, 2014). "The correlation between plasma levels of IL-6 and serum creatinine suggest that IL-6 may play a role in kidney damage in SLE disease or that plasma IL6 was not cleared due to decreased renal function." (PMID 25485543, 2014). "In this study, the extent of kidney damage in the non-treated CKD group, which was more than 4.5-fold higher than controls, was significantly reduced with DTBN treatment, in association with a decrease in key proinflammatory mediators (IL1, IL6, NFkB and STAT3)." (PMID 38555397, 2024). "The study highlights significant differences in vitamin D, vitamin B12, folate, zinc, calcium, IL-6, IL-12, and BDNF between diabetic patients with and without nephropathy." (PMID 41142318, 2025).
kidney damage (continued). "While serum levels of IFN-γ, IL-2, IL-4, and IL-12 did not display a difference between experimental groups (data not shown), expression of IL-5, IL-6, TNF-α, IL-10, CXCL1, and IL-1β was elevated in the NZM2410/J mice displaying signs of severe kidney damage." (PMID 28491039, 2017). "In our study, higher levels of INF-γ, IL-6, and TNF-α were observed in DM1 patients with CKD in comparison to those without nephropathy, which is in agreement with other studies." (PMID 26770985, 2016). "INF-γ, TNF-α, IL6, and IL-10 plasma levels were higher in patients with CKD as compared to those without nephropathy (P = 0.001, P = 0.004, P = 0.016, and P = 0.030, resp)." (PMID 26770985, 2016). "Levels of adiponectin were higher in patients with nephropathy (21.84 ± 8.15 vs 14.88 ± 8.27 mg/ml, p = 0.008), but not regarding the presence of retinopathy; neither TNF- α, nor IL-6 and IL-1β showed differences regarding the presence of microvascular disease." (PMID 26382922, 2015).
osteosarcoma (130 papers, 2009 to 2026). A usually aggressive malignant bone-forming mesenchymal neoplasm, predominantly affecting adolescents and young adults. "In osteosarcomas, elevated levels of cytokines IL-6 and TNF-α have been linked to more aggressive disease, including metastasis and reduced survival." (PMID 40506947, 2025). "For example, lncRNA ST3Gal6 antisense 1 (ST3Gal6-AS1) promotes metabolism of ceramide in osteosarcoma cells, then promoting the polarization of M2 macrophages, leading to higher level of IL-6 and IL-10 and causing immune escape in osteosarcoma." (PMID 39539540, 2024). "It is suggested to be implicated in osteosarcoma initiation and metastasis through upregulating the level of IL-6 and TNF-α." (PMID 34804118, 2021). "Although IL-6 is insufficient to modulate PD-L1 expression, it may be implicated in different functional roles in this osteosarcoma model." (PMID 35326493, 2022). "Associations between inflammatory gene polymorphisms (TNF-α 308G/A, TNF-α 238G/A, TNF-β 252A/G, TGF-β1 29T/C, IL-6 174G/C and IL-10 1082A/G) and osteosarcoma (OS) risk remain unclear." (PMID 29228633, 2017). "Other authors indicated that IL-6, IL-8 and TNF-α are associated with an increased risk of osteosarcoma, and that elevated levels of IL-8 and TNF-α are correlated with the progression of this disease." (PMID 40722593, 2025). "The increased IL-6 and IL-10 in the microenvironment inhibited the function of T cells, inducing immune evasion in osteosarcoma." (PMID 41502512, 2025). "In osteosarcoma, NF-κB regulates two crucial cytokines: interleukin-6 (IL-6) and tumor necrosis factor-alpha (TNF-α)." (PMID 39949765, 2025). "In TAMs, LPAR6 expression was positively correlated with ADGRE5, IL10, and IL6, which was further validated in the osteosarcoma cohort." (PMID 41502512, 2025). "A more recent study using preclinical models of osteosarcoma showed that pulmonary metastasis is initiated by a subpopulation of disseminated tumor cells that produce cytokines such as IL-6 and CXCL8 in response to lung-epithelium-derived IL-1α." (PMID 41008853, 2025). "As the main matrix component in the microenvironment of osteosarcoma, CAFs secrete a large amount of soluble factors such as IL-6, TGF-β, and CXCL12 (also known as SDF-1)." (PMID 40959080, 2025). "Other growth factors and cytokines, including epidermal growth factor (EGF) and interleukin-6 (IL-6), have also been implicated in promoting EMT in osteosarcoma, contributing to enhanced tumor invasion." (PMID 40075892, 2025). "In osteosarcoma, irisin reversed interleukin-6 (IL-6)-induced EMT, leading to a reduction in N-cadherin, vimentin, fibronectin, MMP2, MMP6, and MMP9 expression, alongside STAT3/Snail suppression." (PMID 41002741, 2025). "For instance, a study demonstrated that the STAT3 inhibitor cryptotanshinone effectively reduced tumor progression and improved survival rates in osteosarcoma models by inhibiting IL-6 signaling." (PMID 40909292, 2025). "NF-κB activation in osteosarcoma results in elevated IL-6 production, which subsequently activates the Janus kinase/signal transducer and activator of transcription (JAK/STAT3) pathway." (PMID 39949765, 2025). "EVs from 143B and SAOS2 osteosarcoma cells ‘educate’ murine lungs by inducing CD11b + myeloid cell accumulation and pro-inflammatory IL6 production by mesenchymal stem cells through the selective incorporation of a membrane associated form of TGFβ." (PMID 40442778, 2025). "Recent research has shown that targeting the IL-6/JAK/STAT3 signaling pathway can significantly inhibit osteosarcoma growth and metastasis by reducing tumor self-seeding and enhancing antitumor immunity." (PMID 40909292, 2025). "Further investigation revealed elevated expression of key signaling molecules and pathways, such as epidermal growth factor (EGF) and interleukin-6 (IL-6), in recurrent osteosarcomas compared to their primary counterparts." (PMID 39534688, 2024).
osteosarcoma (continued). "Osteosarcoma cells colonize the lungs more quickly by upregulating ICAM1 expression in response to tumor‐derived IL‐6, which facilitates glycolytic metabolism in tumor cells by activating the MEK/ERK/HIF‐1α pathway." (PMID 36772869, 2023). "Tissue microarrays were established using 104 tumor specimens, and were used to examine IL-6 expression in patients with osteosarcoma by IHC staining." (PMID 37404767, 2023). "Interleukin‐6 (IL‐6) activated the expression of ICAM‐1 and contributed to the migration of human osteosarcoma cells through integrin‐linked kinase (ILK)/Akt/AP‐1 pathways." (PMID 36772869, 2023). "Evidence shows that osteosarcoma cells can release TGFβ-rich extracellular vesicles, which can induce the prometastatic IL-6 production by MSC." (PMID 35361751, 2022). "Combined use of TGF-β inhibitors and IL-6 blockers can reduce drug resistance and prevent the progression of osteosarcoma, which is based on the finding that EVs carry functional TGF-β molecules and elevate IL-6 production, promoting OS growth and metastasis." (PMID 35928720, 2022). "According to the results of this study, and consistent with previous research, high levels of CXCL8/IL8 and IL6 are secreted primarily by cells of the TME and are associated with a poor survival prognosis for patients with osteosarcoma." (PMID 36354566, 2022). "For instance, IL-6 serum levels are high in osteosarcoma patients and the cytokine stimulates osteosarcoma stemness as measured in a self-renewal spheroid assay." (PMID 35205716, 2022). "IL-6 released by activated mesenchymal stem cells (MSCs) in the tumor microenvironment promoted osteosarcoma stemness and the spreading properties of cancer cells." (PMID 35582537, 2022). "Here, we demonstrate that chemotherapeutic agents such as doxorubicin induce EV release, stimulating neighboring cancer cells to express IL-6 and IL-1β in osteosarcoma." (PMID 35326493, 2022). "A first example of such approach is represented by the combined blockade of IL-8 and IL-6 in osteosarcoma." (PMID 36591453, 2022). "IL-6 is also described as responsible for the increased chemoresistance of human osteosarcoma cells and exacerbates the invasive capacity of cells contributing to tumor development when secreted by CAFs." (PMID 36232719, 2022). "We aimed to further verify other phosphoproteins after ensuring the reliability of the corresponding antibodies in order to reveal more possibilities related to drug resistance induced by IL-6 in osteosarcoma." (PMID 34717622, 2021). "Closing the feedback circuit between MSCs and bone sarcoma cells, several works have identified STAT3 as the main pro-stemness and pro-tumorigenic factor induced by MSC-released IL-6 in osteosarcoma cells." (PMID 34198693, 2021). "We also tested two STING-expressing osteosarcoma lines we had previously found to produce IL-6 upon CPT treatment (HOS and MG-63 cells)." (PMID 35087822, 2021). "This is the first study using TMT label-based LC-MS/MS technology on IL-6 intervention before osteosarcoma cells were treated with lobaplatin." (PMID 33791202, 2021). "Cinobufagin inhibited osteosarcoma cell proliferation and tumorigenesis capability via blocking IL6–OPN–STAT3 signaling pathway." (PMID 33436536, 2021). "This is the first report suggesting changes in estrogen as a possible pathway for IL-6-induced resistance to lobaplatin in an osteosarcoma cell model." (PMID 33791202, 2021). "Relevantly, the treatment of osteosarcoma CSCs with cinobufagin, a steroid lactone used in Chinese medicine, was able to reduce their levels of IL-6, p-STAT3 and OPN, resulting in an attenuated stem-like phenotype and decreased tumor growth." (PMID 34198693, 2021).
osteosarcoma (continued). "Nevertheless, the role of hFXR1p in the drug resistance of osteosarcoma cells to lobaplatin, especially in the presence of IL-6, is unclear." (PMID 33791202, 2021). "For example, in osteosarcoma, acidosis can lead to the reprogramming of tumor-recruited MSCs to the secretion of osteosarcoma-supporting mediators, such as IL6, IL8, and NF-κB inflammatory pathway." (PMID 34712663, 2021). "In conclusion, we noted that exogenous IL-6 intervention before lobaplatin treatment resulted in reduced sensitivity of osteosarcoma cells." (PMID 33791202, 2021). "This study is the first to use a TMT-based quantitative phosphoproteomics approach to examine the role of post-translational changes in IL-6-induced lobaplatin resistance in osteosarcoma cells." (PMID 34717622, 2021). "This study was to investigate the changes in phosphoproteins and their related signaling pathways in the process of IL-6-induced chemoresistance to lobaplain in osteosarcoma cells." (PMID 34717622, 2021). "Proteomic analysis has shown great strength for large-scale protein investigations to explain the specific mechanism of the role of exogenous IL-6 in drug treatment for osteosarcoma." (PMID 33791202, 2021). "Low extracellular pH in these tumors induces an increased invasive behavior and promotes the secretion of high levels of Interleukin 6 (IL-6) and IL-8 by mesenchymal stem cells, stimulating osteosarcoma growth and metastasis." (PMID 34830463, 2021). "Meanwhile, elevated levels of GRO-a, MCP-1, IL-6 and IL-8 in the tumor microenvironment promoted osteosarcoma invasion and transendothelial migration via cross-talk between tumor cells and CAFs from hBMMSCs." (PMID 33849537, 2021). "We performed a quantitative phosphoproteomic analysis of the response of SaOS-2 osteosarcoma cells to recombinant human IL-6 (rhIL-6) intervention prior to lobaplatin treatment." (PMID 34717622, 2021). "The exposure of osteosarcoma cell lines (Saos-2, MG-63) to condition media from MSCs elevates IL-6 levels, which further activates the STAT3 signaling pathway, resulting in increased tumor growth." (PMID 34681692, 2021). "Hypoxia and interstitial acidosis are also important in the promotion of osteosarcoma bone metastasis, in part through activation of IL-8, IL-6, NF-κB1, colony-stimulating factors CSF2 and CSF3, BMP-2, CCL5, CXCL5 and CXCL1 in tumor-associated MSCs." (PMID 34831167, 2021). "hBMMSC-secreted IL6 and IL-8 have been shown to increase tumor growth and metastasis in osteosarcomas by activation of the STAT3 and FAK signaling pathways, respectively." (PMID 33849537, 2021). "Osteolytic factors produced by osteosarcoma cells, such as interleukin-6 (IL-6), IL-11, receptor activator of NF-κB ligand (RANKL) and tumor necrosis factor-α lead to bone degradation and in consequence release of TGF-β into the tumor microenvironment." (PMID 32751922, 2020). "IL-6 appears to promote the proliferation, metastasis and angiogenesis of osteosarcoma through several downstream signals including AKT, ERK1/2 MAPK and STAT3." (PMID 32257109, 2020). "Kong and colleagues showed that irisin treatment of osteosarcoma cells inhibited the proliferation, migration and invasion of osteosarcoma cells by reversing IL-6-induced EMT." (PMID 32257109, 2020). "Another study revealed that visfatin induced migration of osteosarcoma cells and upregulation of IL-6 through nuclear factor kappa B (NF-κB)." (PMID 31396538, 2019). "NF-κB activation via IKKβ/IκBα signaling was involved in the visfatin-induced migration of osteosarcoma cells and IL-6 upregulation." (PMID 31396538, 2019). "Hypoxic microenvironment also leads to increased interleukin-6 expression in osteosarcoma cells, which contributes to increased lung metastases." (PMID 31370265, 2019). "Second, the intermediate molecular mechanisms underlying the link between IL-6 and TIMP3 and the downstream signaling of TIMP3 in osteosarcoma should be better clarified." (PMID 29731768, 2018).